STIM1 (stromal interaction molecule 1)
Diseases named in the same sentence as STIM1 in open-access papers (continued):
Sharing a sentence is not in itself a finding about the gene and the disease.
breast carcinoma (continued). "However, SPCA2 is over-expressed in the plasma membrane of breast cancer cells, where it directly binds to and activates Orai1, independent of STIM1, and leads to enhanced Ca2+ entry and Ca2+-dependent proliferation." (PMID 32825277, 2020). "Although STIM1 has been reported to affect focal adhesion turnover and rearrangement in several types of cancer cells, the role of STIM2 in regulating EMT and metastasis in breast cancer is unknown." (PMID 31464639, 2019). "In breast cancer MDA-MB-231 cells, upregulation of Orai1 or STIM1 significantly increased the in vitro migratory capability and tumor metastasis potential in mice, whereas silencing of Orai1 or STIM1, as well as SOCE blockade with SKF-96365, attenuated these effects." (PMID 31252656, 2019). "In breast cancer cells, however, Orai1 gating is independent on Stim1 and is not driven by ER Ca2+ store depletion; accordingly, Orai1 is activated by the Secretory Pathway Ca2+-ATPase, SPCA2, in MCF-7 cells and by a yet to be identified mechanism in MDA-MB-435 cells." (PMID 30123430, 2018). "However analysis of clinical data argue against Ago2-dependent STIM1 upregulation as a consistent mechanism supporting breast cancer progression, because even in the most aggressive basal-like subtype there is no negative correlation between Ago2 and STIM1 expression." (PMID 31506588, 2019). "In addition, depletion of Ca2+ from the ER may drive tumor growth by inducing Ca2+ influx through the plasma membrane, as the expression of the SOCE canonical components STIM1 and ORAI1 is augmented in various cancer types, including breast cancer, glioblastoma, melanoma, and esophageal carcinoma." (PMID 25710007, 2015). "Another study, based on the microarray data analyses of 295 breast cancer patients, also showed that transcriptionally-defined basal-like tumors, which have a poor prognosis and lack of effective therapies, are characterized by high STIM1 and low STIM2 mRNA expressions." (PMID 23594099, 2013). "This suggests that STIM1 is not required to enhance SK3 currents by Orai1, similar as reported for breast cancer cells." (PMID 34944977, 2021). "Consistent with the in vitro model, there was no consistent change in Orai1, STIM1, or STIM2 transcript levels in CAFs and NFs in paired breast cancer patient samples." (PMID 34208665, 2021). "Because knockdown or overexpression of STIM1 did not affect the expression of EMT markers in breast cancer cells, we conclude that STIM2, but not STIM1, regulates EMT in breast cancer cells." (PMID 31464639, 2019). "Moreover, silencing ORAI1, but not STIM1, sensitizes MDA-MB-231 basal breast cancer cells to staurosporine-induced apoptosis." (PMID 35682546, 2022). "Interestingly, in breast cancer cells, the second member of the CRAC channel, STIM1, does not play a significant role in these processes, suggesting a distinct pathway of Ca2+ signaling in breast tumors." (PMID 36612099, 2022). "Second, we found that STIM2, but not STIM1, promotes EMT in metastatic breast cancer cells." (PMID 31464639, 2019). "Therefore, STIM2 and STIM1 may regulate different signaling pathways (SOCE and non-SOCE), with STIM2 playing a more important role in regulating breast cancer cell motility and promoting metastasis." (PMID 31464639, 2019). "Conversely, no functional role has so far been established for Stim1 and Orai1 paralogues, that is, Stim2 and Orai2, in carcinogenesis, while Orai3 is recruited by Stim1 to activate SOCE and cell proliferation in some oestrogen receptor-negative human breast cancer lines." (PMID 25126575, 2014).
cervical carcinoma (37 papers, 2012 to 2025). A carcinoma arising from either the exocervical squamous epithelium or the endocervical glandular epithelium. "Knockdown of STIM1 in cervical cancer (SiHa and HeLa) caused inhibition of CDK2 phosphorylation, increase in cyclin inhibitors p21 and p27, and accumulation of Cyclin E." (PMID 34572262, 2021). "Consistent with our results, increase in STIM1 expression has been observed in various cancer cells and has been associated with the risk of metastasis in cervical cancer." (PMID 27793015, 2016). "Dysregulated expression of ORAI1 and STIM1 genes was found in several types of cancer and has been linked to more aggressive forms of breast and cervical cancer." (PMID 23922331, 2013). "For example, a study in the model of human cervical cancer indicated that the microtubule-associated histone deacetylase 6 (HDAC6) has different regulatory effects on the microtubule-dependent STIM1 translocation and SOCE activation between cancerous and noncancerous epithelial cells." (PMID 31252656, 2019). "In addition, cervical cancer patients with pelvic lymph-node metastasis, which is the primary cause of treatment failure and subsequent death in cervical cancer patients, displayed higher STIM1 expression in tumor tissues." (PMID 23594099, 2013). "In HPV-positive cervical cancer, STIM1 overexpression leads to increased VEGF-A (vascular endothelial growth factor) production, which facilitates cancer cell invasion." (PMID 40361464, 2025). "CRAC channels, particularly STIM1 and Orai1, play crucial roles in the progression of cervical cancer." (PMID 40361464, 2025). "STIM1 overexpression promotes cervical cancer cell invasion, whereas its knockout decreases its migratory potential." (PMID 40361464, 2025). "The excessive expression of STIM1 enhances the invasion of cervical cancer cells, while the knockout of STIM1 weakens this migration." (PMID 36230965, 2022). "STIM1′s expression in tumors is also closely related to the clinical prognosis of early cervical cancer." (PMID 36230965, 2022). "Given the importance of SOCE tumor biology and cancer progression, it is plausible to suggest that the blockade of STIM1/Orai1-dependent Ca2+ signaling can be a practical therapeutic approach for cervical cancer." (PMID 35008759, 2021). "The distinct distribution of overexpressed STIM1 was identified in the invasive tumor front of the surgical specimens of human cervical cancer." (PMID 35008759, 2021). "Measurement of the secretions of vascular endothelial growth factor (VEGF), a potent inducer of vascular endothelial cell proliferation and migration, showed that STIM1 expression regulated VEGF-A productions from cervical cancer cells." (PMID 35008759, 2021). "Results from the mouse tumor xenograft model of cervical cancer showed that STIM1 silencing or SOCE blockade resulted in a reduction in tumor neovascularization and tumor growth." (PMID 35008759, 2021). "Studies on human cervical cancer have revealed that patients with STIM1 upregulated primary tumors have poorer clinical outcomes due to excessive tumors and lymph node metastasis." (PMID 34572262, 2021). "Results from STIM1 overexpression or silencing, as well as the pharmacological blockade of SOCE in cervical cancer, showed that STIM1-mediated SOCE is crucial for the migratory capability of cervical cancer cells." (PMID 35008759, 2021). "The functional significance of STIM1-dependent SOCE in tumor angiogenesis supporting the progression of cervical cancer was revealed from the study using the model of SiHa cervical cancer cells." (PMID 35008759, 2021). "In cervical cancer, inhibition of STIM1 resulted in increased expression of p21, and arrested the cells in the S- and G2/M phase of the cell cycle." (PMID 34155535, 2021). "Among the patients suffering from colorectal cancer, gastric cancer, cervical cancer, a correlation between STIM1 and/or Orai1 expression levels and poor prognosis with fast metastatic progression has been detected." (PMID 33333945, 2020).
cervical carcinoma (continued). "STIM1 expression was up-regulated in 71% of early stage cervical cancer and the level of expression in primary tumour tissue was linked to the occurrence of pelvic lymph node metastasis and poor patient survival." (PMID 32825277, 2020). "The functional significance of STIM1/Orai1-dependent SOCE in tumor angiogenesis was confirmed by a study using the model of SiHa cervical cancer cells." (PMID 31252656, 2019). "The secretion of VEGF of cervical cancer cells correlated with STIM1 expression levels, as demonstrated by overexpression or RNAi-mediated manipulation of STIM1 levels." (PMID 31252656, 2019). "Consistently, the overexpression of STIM1 enhances cell migration in cervical cancer and colorectal cancer." (PMID 30935064, 2019). "In a mouse tumor xenograft model of cervical cancer, STIM1 silencing or SOCE blockade resulted in a reduction in tumor neovascularization, and tumor growth." (PMID 31252656, 2019). "Cell cycle arrest in the G0/G1 phase in U251 cells, in neck squamous cell carcinoma cell lines, and at the S and G2/M phases in cervical cancer cells by STIM1-silencing has been reported." (PMID 30935064, 2019). "The studies in human cervical cancer indicated that STIM1 upregulation in primary tumors was significantly correlated with the poorer clinical outcomes, such as larger tumor size and elevated lymph node metastasis." (PMID 31252656, 2019). "The pro-proliferative role of STIM1 in vivo was further demonstrated by STIM1-knockdowned xenografts of human glioblastoma or cervical cancer, which exhibited an attenuated growth rate as compared to control tumors." (PMID 31252656, 2019). "We observed that STIM1 depletion also decreased CDDP-induced cell death in cervix carcinoma cells HeLa, as demonstrated by the reduction of the percentage of cells with low ΔΨm and the reduction in PARP cleavage." (PMID 30917547, 2019). "Upregulated VEGF production by a high STIM1 expression in human cervical cancer cells regulates the focal-adhesion dynamics of migratory cells." (PMID 30935064, 2019). "Studies in cervical cancer showed that STIM1-dependent SOCE is crucial for the migratory capability of cancer cells, as demonstrated by results from overexpression or silencing of STIM1 as well as the blockade of SOCE by 2-APB and SKF-96365." (PMID 31252656, 2019). "Tumor nest was formed when cervical carcinoma invaded deeply into stromal tissues, where STIM1 was also abundant." (PMID 28912430, 2017). "Our previous study showed that STIM1/Orai1-dependent SOCE enhances the cell migration of cervical cancer cells through activating the Ca2+-dependent protease calpain and tyrosine kinase Pyk219." (PMID 28912430, 2017). "For example, epidermal growth factor (EGF)-stimulated cervical cancer cell migration requires STIM1 expression, and the inhibition of SOCE suppresses EGF-induced migration and eliminates extravasation from the vasculature in nasopharyngeal carcinoma cells." (PMID 26919241, 2016). "Time-lapse fluorescent images of cervical cancer SiHa cells overexpressing fluorescently-tagged STIM1 or STIM2 were employed to study the dynamics of STIM proteins in SOCE activation." (PMID 26917047, 2016). "STIM1 also regulates cell growth, migration, and angiogenesis in cervical cancer cells, and STIM1 knockdown suppresses cell proliferation and tumorigenicity in human epidermoid carcinoma A431 cells." (PMID 26919241, 2016). "STIM1 or STIM2 knockdown by different siRNA duplexes in cervical cancer SiHa cells was accompanied by a significant decrease of SOCE activation." (PMID 26917047, 2016). "Recently, STIM1 has been shown to be essential for cervical cancer growth, migration, and angiogenesis as well as human glioblastoma cell proliferation and cell cycle regulation." (PMID 26919241, 2016). "In cervical cancer cells STIM1 silencing abrogates proliferation and induces cell cycle arrest at the S and G2/M phase." (PMID 25015419, 2014).
cervical carcinoma (continued). "Similar molecular and pharmacologic approaches employed in this study have been utilized by other investigators to evaluate the importance of STIM1 to the migration and metastasis of breast and cervical cancers." (PMID 24797725, 2014). "More importantly, STIM1-dependent Ca2+ signalings control cervical cancer cell migration by the regulation of actomyosin reorganization in conjunction with enhanced contractile forces." (PMID 23594099, 2013). "The levels of STIM1 expression in tumor tissues were closely correlated with the primary tumor size, an important indicator of human cervical carcinoma progression in vivo." (PMID 23594099, 2013). "The functional significance of STIM1 and Orai1 in tumor progression in vivo has been revealed in breast and cervical cancer." (PMID 23594099, 2013). "STIM1-dependent Ca2+ signalings also play an important role in epidermal growth factor (EGF)-stimulated cervical cancer cell migration." (PMID 23594099, 2013). "Mechanistic investigations revealed that the secretion of vascular endothelial growth factor (VEGF), a critical stimulator for tumor angiogenesis, from cervical cancer cells was dependent on their STIM1 expressions." (PMID 23594099, 2013). "STIM1 overexpression significantly enhanced tumor growth, local spread and angiogenesis of human cervical cancer xenograft in SCID mice, whereas shRNA-mediated knockdown of STIM1 significantly decreased tumor growth and tumor vessel numbers." (PMID 23594099, 2013). "Among 71% cases of early-stage cervical cancer examined, STIM1 protein expression was upregulated in cervical cancer tissues but rarely detected in adjacently non-cancerous cervical epithelia." (PMID 23594099, 2013). "The knockdown of STIM1 inhibited tumor progression in a cervical cancer mouse model." (PMID 36555115, 2022). "STIM1 is very important for cervical cancer cell proliferation, migration, and vascular generation." (PMID 36230965, 2022). "STIM1 silencing in cervical cancer cells can significantly inhibit cancer cell proliferation." (PMID 36230965, 2022). "Indeed, silencing STIM1 attenuates invasive migration of cervical cancer cells, whereas overexpressed STIM1 enhances it." (PMID 36612099, 2022). "STIM1 overexpression has been reported to play important roles in the progression of many severe diseases, including several malignancies, such as pancreatic, breast, and cervical cancer." (PMID 35891504, 2022). "Moreover, the function of the Pyk2 kinases and the protease calpain, which control cytosolic scaffold proteins (e.g., α-spectrin) and thus focal adhesion dynamics, is modulated by STIM1 in migratory cervical cancer cells." (PMID 36612099, 2022). "Regarding the role of STIM2 in cervical cancer cell proliferation, results from the individual or simultaneous silencing of STIM1/STIM2 suggested that both STIM1 and STIM2 contribute to the cell proliferation, at least partly through the regulation of SOCE during G1/S transition." (PMID 35008759, 2021). "A similar role for STIM1/ORAI mediated SOCE has been observed in cervical cancer, hepatocellular carcinoma, renal cell carcinoma, nasopharyngeal cancer, and glioblastoma where this Ca2+ influx regulates focal adhesion turnover, cytoskeletal reorganization, and actomyosin-based mechanotransduction." (PMID 34572262, 2021). "Furthermore, the growth of human cervical cancer xenograft in the SCID mice was attenuated by the interference with STIM1 expression or blockade of SOCE activity, demonstrating the in vivo significance of SOCE in cell proliferation." (PMID 35008759, 2021). "In addition, STIM1 has been shown to be important for cervical cancer cell proliferation, migration, and angiogenesis." (PMID 32825277, 2020). "Furthermore, there is a positive correlation of local migration, tumor size and angiogenesis with STIM1 levels in cervical cancers cells." (PMID 32733237, 2020).
cervical carcinoma (continued). "Interestingly, the specific distribution of overexpressed STIM1 in the invasive tumor front was identified in a recent study on human cervical cancer." (PMID 31252656, 2019). "Regarding the role of STIM2 in cell cycle regulation, results from the individual or simultaneous silencing of STIM1/STIM2 in cervical cancer cells suggested that both STIM1 and STIM2 are involved in the regulation of SOCE during G1/S transition, and thus contribute to cell proliferation." (PMID 31252656, 2019). "Pharmacological or siRNA inhibition of the STIM1/Orai1 pathway of SOCE activation in human cervical cancer cells resulted in the decreased phosphorylation of CDK2 and the excursive expression of cyclin E, leading to autophagy accompanied with a cell cycle arrest in G1/S transition." (PMID 31252656, 2019). "However, a very recent study on cervical cancer SiHa cells showed that STIM1 and STIM2 displayed different kinetic characteristics during SOCE activation." (PMID 31252656, 2019). "However, the SOCE of primary cervical cancer cells was more active, which is consistent with the molecular evidences demonstrating overexpressed STIM1 in cancer tissues." (PMID 28912430, 2017). "Interestingly, STIM1 was abundant at the invasive front of cervical carcinoma, an area where squamous cell carcinoma just broke through the basal layers of squamous epithelia." (PMID 28912430, 2017). "A previous study proposed that posttranslational regulation via the 26S-proteasome-dependent pathway might contribute to the mechanisms controlling p21 upregulation in STIM1-knock-down cervical cancer cells." (PMID 27863410, 2016). "The significance of STIM1 in cellular migration may extend beyond breast and cervical cancer given its role in the migration and focal adhesion turnover in hepatocarcinoma cells." (PMID 23594099, 2013). "That is why elevated STIM1 expression could serve as a valuable biomarker for cervical cancer." (PMID 40361464, 2025). "Interestingly, the expression of STIM1 and Orai1 was increased in most cervical cancer specimens, while the acetylation of tubulin was decreased, suggesting that specific targeting of HDAC6 in cervical cancer can inhibit STIM1-Orai1-mediated cervical neogenesis." (PMID 36230965, 2022). "The studies in human cervical cancer indicated that poorer clinical outcomes, such as larger tumor size and elevated lymph node metastasis, are correlated with STIM1 upregulation in primary tumors, highlighting the clinical significance of STIM1 in cervical cancer progression." (PMID 35008759, 2021). "Therefore, using the STIM1/STIM2 ratio as a marker of cervical cancer aggressiveness might be promising and worth further evaluation." (PMID 35008759, 2021). "Furthermore, STIM1 knockdown significantly inhibited cell proliferation of human cervical cancer cells by slowing down the cell cycle progression accompanied by increasing cyclin-dependent kinase inhibitor p21 protein and decreasing phosphatase Cdc25C protein levels." (PMID 31252656, 2019). "The down-regulation of STIM1 decreased the EGF-induced phosphorylation of PyK2 and enhanced the focal adhesion of cervical cancer cells (SiHa)." (PMID 36555115, 2022). "In cervical cancer, a recent study found that histone deacetylase 6 (HDAC6) is required for STIM1 translocation on microtubules and thus activates Orai1-mediated SOCE." (PMID 36230965, 2022). "Aberrated overexpression of STIM1 or Orai1 and thus upregulated SOCE activity have been observed in several types of human cancers, including cervical cancers." (PMID 35008759, 2021). "In fact, STIM1 expression level is enhanced in early-stage cervical cancers, and using STIM1 siRNA, both SOCE and proliferation were inhibited in the cervical cancer cells." (PMID 32733237, 2020). "STIM1 knockdown using shRNA and SOCE blockers (2-APB and SKF96365) reduced cervical cancer growth and the number of tumour blood vessels in cervical cancer xenograft mouse models." (PMID 32825277, 2020).